ASAH1 (N-acylsphingosine amidohydrolase 1)
Diseases named in the same sentence as ASAH1 in open-access papers (continued):
Sharing a sentence is not in itself a finding about the gene and the disease.
melanoma (continued). "Collectively, these results demonstrate that ASAH1 is a druggable driver of melanoma tumor growth and metastasis that functions by suppressing peroxisome biogenesis, thereby inhibiting peroxisome-derived ROS production." (PMID 33766731, 2021). "When comparing previously published gene expression profiles of patient-derived melanoma samples with normal skin, we found a significant upregulation of ASAH1 in the melanoma samples, and ASAH1 levels increased as melanoma progressed." (PMID 33766731, 2021). "Pharmacological inhibition of ASAH1 also attenuated melanoma growth and enhanced the effectiveness of BRAF kinase inhibitor in the cell cultures and mice." (PMID 33766731, 2021). "Collectively, our studies demonstrated that the metabolic enzyme ASAH1 promotes melanoma growth through suppressing peroxisome biogenesis and attenuating peroxisome-induced ROS production." (PMID 33766731, 2021). "Collectively, these results show that the MAPK pathway transcriptionally upregulates ASAH1 expression in melanoma." (PMID 33766731, 2021). "We also demonstrate that pharmacological ASAH1 inhibition blocks melanoma growth and increases the effectiveness and therapeutic duration of a BRAF kinase inhibitor." (PMID 33766731, 2021). "We used publicly available melanoma datasets and patient-derived samples of melanoma and normal skin tissue and analyzed them for ASAH1 mRNA expression and ASAH1 protein expression using immunohistochemistry." (PMID 33766731, 2021). "shRNA-resistant wild-type ASAH1 rescued tumor growth in the melanoma cell line expressing ASAH1 shRNA, whereas the shRNA-resistant enzymatically defective ASAH1 mutant did not." (PMID 33766731, 2021). "Simultaneous knockdown of PPARγ and ASAH1 inhibited the ability of C2 ceramide or rosiglitazone to activate PPAR-responsive firefly-luciferase reporter activity in melanoma cells." (PMID 33766731, 2021). "We found that over 50% of the melanoma samples had higher ASAH1 expression compared with the normal skin samples." (PMID 33766731, 2021). "Collectively, these results demonstrate that the ASAH1-driven ceramide metabolism pathway can be inhibited pharmacologically to treat melanoma and enhance outcomes when combined with other targeted therapeutics, such as BRAF kinase inhibitors." (PMID 33766731, 2021). "ASAH1 knockdown in melanoma cells increased peroxisomal ROS levels compared with cells expressing non-specific shRNA." (PMID 33766731, 2021). "Collectively, these results demonstrate that genetic inhibition of ASAH1 attenuates melanoma tumor growth and metastatic growth in lungs." (PMID 33766731, 2021). "Treatment of ASAH1-knockdown melanoma cells with NAC rescued melanoma growth in soft agar, demonstrating that the ASAH1 knockdown-induced increase in peroxisomal ROS plays a role in inhibiting melanoma growth." (PMID 33766731, 2021). "Once we established the role of ASAH1 in melanoma tumor growth and metastasis and the mechanism driving its overexpression, we investigated the mechanism by which ASAH1 promotes tumor growth." (PMID 33766731, 2021). "We also showed that melanoma cells depend on the enzymatic activity of ASAH1 and that its expression is necessary for melanoma tumors and metastatic growth in mice." (PMID 33766731, 2021). "We also found that ASAH1 expression increased with tumor progression as observed by increased ASAH1 mRNA expression levels with increasing melanoma stages." (PMID 33766731, 2021). "In the present study, we monitored the effect of ceramide on peroxisome biogenesis and showed that this is important for mediating the effect of ASAH1 on melanoma growth." (PMID 33766731, 2021). "Similar increases in PMP70 and ceramide levels and decreases in pipecolic acid levels were also observed in tumors derived from ASAH1 shRNA expressing A375 and M14 melanoma xenografts." (PMID 33766731, 2021). "The involvement of ASAH1 in mitochondrial function and cellular autophagy in melanoma cells has been observed." (PMID 34357010, 2021).
melanoma (continued). "Collectively, these results suggest a potentially important role of ASAH1 in melanoma tumor growth and metastasis." (PMID 33766731, 2021). "To identify the mechanism by which ASAH1 facilitates melanoma tumor growth and metastasis, we performed a large-scale and unbiased metabolomics analysis of melanoma cells expressing ASAH1 short-hairpin RNAs (shRNAs)." (PMID 33766731, 2021). "Incidentally, the ACDase activity is significantly more upregulated than the ASAH1 expression in melanoma cells." (PMID 32498325, 2020). "ASAH1 expression was: (i) higher in human melanoma cell lines exhibiting a proliferative phenotype as compared to invasive ones; and (ii) reduced at the invasive front on tumour specimens from melanoma patients." (PMID 32858889, 2020). "In fact, the benefit of developing an auto-ASAH1 antibody has already been documented in melanoma patients." (PMID 29642535, 2018). "It was found that melanoma patients who had an auto anti-ASAH1 antibody were protected from lymph node metastasis." (PMID 29642535, 2018). "In a genomic study, ASAH1 was found to be a useful biomarker for cancer detection and identification in cases of melanoma." (PMID 29642535, 2018). "To overcome this limitation, in the present study we used CrispR/Cas9-mediated gene editing to remove the ASAH1 gene and its protein product from A375 melanoma cells, which are known for their high invasiveness and self-renewal capabilities." (PMID 28785021, 2017). "We identified 5 melanoma-associated antigens using this microarray coupled to mass spectrometry; GRP75, GRP94, ASAH1, CTSD and LDHB." (PMID 22084687, 2011). "ASAH1, an enzyme that hydrolyses ceramides, is significantly overexpressed in melanoma samples." (PMID 38244103, 2024). "In addition, ASAH1-null cells lose the ability to form cancer-initiating cells in melanoma, suggesting its crucial role in malignancy maintenance." (PMID 38926346, 2024). "Accordingly, low CERS6 and high ASAH1 in human cutaneous melanoma may contribute to the low ceramide accumulation in melanoma." (PMID 36077841, 2022). "We next evaluated whether ASAH1 inhibition affects the sensitivity of melanoma cells to BRAF kinase inhibitors." (PMID 33766731, 2021). "We have also identified a new role for ASAH1 in promoting melanoma growth." (PMID 33766731, 2021). "Because genetic inhibition of ASAH1 inhibited melanoma growth, we investigated whether a pharmacological ASAH1 inhibitor could similarly inhibit melanoma growth." (PMID 33766731, 2021). "We next determined the mechanism leading to ASAH1 overexpression in melanoma." (PMID 33766731, 2021). "To test whether ASAH1 is necessary for tumor growth, we knocked down ASAH1 expression in multiple melanoma cell lines (A375, M14, MeWo, and YUGASP) using shRNAs and evaluated anchorage-independent growth using a soft-agar assay." (PMID 33766731, 2021). "However, the role of ASAH1 in melanoma growth and progression and its mechanism of action are unclear." (PMID 33766731, 2021). "To further verify the role of ASAH1 in melanoma tumor growth, we performed in vivo experiments." (PMID 33766731, 2021). "In this report, we show that ASAH1 is required for melanoma tumor growth and metastasis." (PMID 33766731, 2021). "•ASAH1 inhibitor blocks melanoma and enhances the effectiveness of BRAF inhibitor." (PMID 33766731, 2021). "ASAH1 was knocked down using short-hairpin RNAs in multiple melanoma cell lines that were tested in a series of cell culture-based assays and mouse-based melanoma xenograft assays to monitor the effect of ASAH1 knockdown on melanoma tumor growth and metastasis." (PMID 33766731, 2021). "First, we tested whether ASAH1 knockdown alters the sensitivity of BRAF-mutant melanoma cells to the BRAF kinase inhibitor vemurafenib in vitro." (PMID 33766731, 2021). "Therefore, we investigated if the MAPK pathway activity is required for transcriptional ASAH1 overexpression in melanoma." (PMID 33766731, 2021).
melanoma (continued). "As expected, ASAH1 knockdown increased ceramide levels in melanoma cells." (PMID 33766731, 2021). "We next investigated whether the acid ceramidase activity of ASAH1 is required for melanoma tumor growth." (PMID 33766731, 2021). "•ASAH1 is necessary for melanoma tumor growth and metastasis." (PMID 33766731, 2021). "ASAH1 is overexpressed in many cancer types, including melanoma." (PMID 33766731, 2021). "Similarly, when evaluating profiles from a panel of multiple cancer cell lines, ASAH1 expression was significantly higher in the melanoma cell lines." (PMID 33766731, 2021). "•Transcription factor E2F1 regulates ASAH1 expression in melanoma." (PMID 33766731, 2021). "Because ASAH1 is an enzyme for which small-molecule inhibitors are available, its inhibition could be a pharmacologically tractable approach for treating melanoma." (PMID 33766731, 2021). "Based on previous literature, AAb against ASAH1 could be applied to monitor the progression of melanoma." (PMID 32616055, 2020). "We used the CrispR/Cas9 system to delete the ASAH1 gene in A375 melanoma cells." (PMID 28785021, 2017). "Therefore, we believe this aspect of ASAH1 function is critical for its function in promoting melanoma; however, it is also worth noting that we measured the effect of ASAH1 inhibition in our experiments in which ceramide accumulated and showed that it has a tumor-suppressive effect." (PMID 33766731, 2021). "In line with this interesting effect, deletion of ASAH1 using CRISPR-Cas9 in A375 melanoma cells was found to disrupt ceramide metabolism and directed cells towards either apoptosis or senescence, suggesting that ASAH1 may potentially be a therapeutic target for both cancer and senescence." (PMID 34102611, 2021). "Furthermore, to test whether the increased ROS production resulting from ASAH1 knockdown contributes to the inhibition of melanoma growth, we treated cells with antioxidant N-acetylcysteine (NAC) and performed soft-agar assays." (PMID 33766731, 2021). "Therefore, we investigated if ASAH1 expression plays a role in melanoma metastasis in vivo." (PMID 33766731, 2021). "In addition, the expression of ASAH1 is greater in proliferative than invasive melanomas." (PMID 31336922, 2019). "Finally, we used RT-PCR to evaluate possible changes in melanoma markers induced by ASAH1 deletion." (PMID 28785021, 2017). "Importantly, ASAH1-null cells also lose the ability to form cancer-initiating cells and to undergo self-renewal, which is suggestive of a key role for AC in maintaining malignancy and self-renewal of invasive melanoma cells." (PMID 28785021, 2017). "For example, melanoma cells with ASAH1 ablated via CRISPR-Cas9 gene editing lost the ability to self-renew and create cancer-initiating cells, highlighting ACDase’s role in autophagy, mitochondrial homeostasis, and maintaining malignancy." (PMID 36830643, 2023). "Additionally, we assessed whether ASAH1 knockdown affects melanoma metastasis." (PMID 33766731, 2021). "In melanoma, low levels of MITF are accompanied by low levels of ASAH1 expression, which correlates with invasive behavior and worse prognosis." (PMID 31336922, 2019). "Consistent with our soft-agar results, knockdown of ASAH1 significantly inhibited melanoma tumor growth compared with non-specific shRNA in vivo." (PMID 33766731, 2021). "ROS levels were higher in melanoma cells expressing ASAH1 shRNA than those expressing non-specific shRNA." (PMID 33766731, 2021). "We administered melanoma cells expressing ASAH1 or non-specific shRNA via the tail vein in NOD-SCID gamma (NSG) mice." (PMID 33766731, 2021). "ASAH1 knockdown significantly reduced the ability of various melanoma cells to form colonies compared with cells expressing non-specific shRNA." (PMID 33766731, 2021).
melanoma (continued). "Based on our finding that N-acylsphingosine amidohydrolase 1 (ASAH1) is overexpressed in melanoma, the objective of these studies was to establish its role in melanoma tumor growth and metastasis, understand its mechanism of action, and evaluate ASAH1 targeting for melanoma therapy." (PMID 33766731, 2021). "We injected various melanoma cell lines (A375, M14, MeWo, and YUGASP) expressing either ASAH1 shRNAs or a non-specific shRNA subcutaneously into the flanks of the athymic nude mice and monitored melanoma tumor growth." (PMID 33766731, 2021). "Knockdown of ASAH1 did not significantly affect the invasiveness or migration of melanoma cells compared with cells expressing non-specific shRNA but did induce anoikis." (PMID 33766731, 2021). "In tail vein-based experiments mirroring lung colonization, ASAH1 knockdown significantly decreased the metastatic growth of melanoma cells in the lungs compared with cells expressing non-specific shRNA." (PMID 33766731, 2021). "We then measured PPAR activity using a PPAR-responsive element (PPRE)-driven firefly-luciferase reporter in melanoma cells expressing ASAH1 or non-specific shRNA." (PMID 33766731, 2021). "We treated melanoma cells expressing ASAH1 shRNAs or non-specific shRNA with C2 ceramide, a cell-permeable ceramide analog, to mimic the ceramide levels seen with ASAH1 knockdown." (PMID 33766731, 2021). "To determine whether E2F1 regulates ASAH1 transcription, we knocked down E2F1 expression in the melanoma cell lines A375 and M14." (PMID 33766731, 2021). "Prior to this publication, the third protein, acid ceramidase (ASAH1), had not been strongly associated with melanoma progression, but has been associated with cancers of the breast, prostate, and thyroid." (PMID 22084687, 2011). "Furthermore, rosiglitazone-stimulated PPAR-responsive firefly-luciferase reporter activity was higher in melanoma cells expressing ASAH1 shRNAs compared with those expressing non-specific shRNA." (PMID 33766731, 2021).
prostate carcinoma (29 papers, 2008 to 2025). A carcinoma that arises from epithelial cells of the prostate gland. "Stable knockdown of ASAH1 in a prostate cancer cell line (PC-3/Mc) caused accumulation of ceramides, an increased requirement for growth factors, and inhibition of tumor cell proliferation and migration." (PMID 32236130, 2020). "Applying that understanding to prostate cancer PDXs, ASAH1 inhibition sensitized cells to radiation and prevented recurrence." (PMID 38086808, 2023). "Consistently, ASAH1 is upregulated in prostate cancer cell lines as well as in human tissue following radiation." (PMID 38086808, 2023). "ASAH1 is necessary for the growth of metastatic prostate cancer, and ASAH1 expression has been observed to be higher in more advanced stages of prostate cancer." (PMID 33766731, 2021). "White-Gilbertson and his colleagues found that the expression of acid ceramidase (ASAH1) is elevated in PGCC induced by radiation from both prostate cancer and lung cancer." (PMID 34527590, 2021). "For example, ASAH1 is a critical regulator in the case of prostate cancer progression, and when it is suppressed by the knocking down of ASAH1 using siRNA, this results in the amelioration of tumor growth and sensitization toward chemotherapy." (PMID 31817238, 2019). "Investigators reported that, in prostate cancer, over-expression of ASAH1 leads to larger tumor volumes that are more resistant to chemotherapy." (PMID 29642535, 2018). "ASAH1 inhibitors can also function as radiosensitizers, as suggested by a study that illustrated the suppressed growth of prostate cancer xenografts compared with conventional radiation therapy when mice were given ASAH1 inhibitor B13." (PMID 29642535, 2018). "Prostate cancer upregulates ASAH1 following radiation, which was described as a mechanism enabling the cancer to survive radiation." (PMID 29642535, 2018). "The significant role of ASAH1 in tumor progression and invasion has been well characterized in the prostate cancer cell line DU145." (PMID 29348854, 2017). "ASAH1 has been shown to play a significant role in tumor progression in many cancers, including melanoma, colon, and prostate cancers." (PMID 29348854, 2017). "The growth of prostate cancer xenografts was significantly suppressed compared to conventional radiation therapy when mice were treated with B13, an ASAH1 inhibitor, and radiation, suggesting a synergistic role between these inhibitors and radiation." (PMID 29348854, 2017). "ASAH1 expression has been positively correlated with Akt phosphorylation in prostate cancer tissues." (PMID 24970218, 2014). "Acid ceramidase (ASAH1) up-regulation has been reported in prostate cancer, correlating with tumour grade, malignant gliomas, HNSCC, and T-cell large granular lymphocytic (LGL) leukaemia." (PMID 24970218, 2014). "ASAH1 degradation was found to be controlled by the proteasome in a prostate cancer cell line." (PMID 33884955, 2021). "More importantly, ASAH1 inhibitors have been proposed as radiosensitizers, on the basis of studies that illustrated a greater suppression of the growth of U87 and prostate cancer xenografts when treated with both conventional radiation therapy and ASAH1 inhibitors." (PMID 29899215, 2018). "Interestingly, ASAH1 maps to chromosome 8p22, which is frequently deleted in prostate cancer patients." (PMID 26473288, 2015). "Interestingly, over-expression of ASAH1 in prostate cancer promotes resistance to chemotherapy." (PMID 29899215, 2018). "As in PPC1 prostate cancer cells, we detected a highly significant increase in INSIG1 mRNA and a smaller, but also significant increase in HMGCR following ASAH1 inhibition in PGCC." (PMID 35624221, 2022). "Increased secretion of ASAH1 was also found in prostate cancer, but not in nonmalignant cells, affording a certain capacity to distinguish between prostate cancer and nonmalignant cells." (PMID 29642535, 2018).
prostate carcinoma (continued). "Although ASAH1 is a non-secreted lysosomal enzyme in normal tissue, it becomes dysregulated in prostate cancer cells and is secreted into the culture media exclusively by prostate cancer cells." (PMID 29348854, 2017). "The first additional database is the prostate cancer cell line (PPC1) with radiation-induced PGCC, treated or non-treated with pro-drug LCL521, which is an inhibitor of lysosomal enzyme acid ceramidase ASAH1." (PMID 41287033, 2025).